TRIM24 (tripartite motif containing 24)
Diseases named in the same sentence as TRIM24 in open-access papers (continued):
Sharing a sentence is not in itself a finding about the gene and the disease.
tumor (continued). "Existing research showed that down-regulation of TRIM24 might promote tumor development through complex mechanisms." (PMID 24409330, 2014). "TRIM24 could also bind chromatin and oestrogen receptor to activate oestrogen-dependent genes so as to regulate cellular proliferation and tumor progress." (PMID 24409330, 2014). "In addition to TRIM24::NTRK2 and CDKN2A/B HD, a SLC6A14 missense variant (p.R614H) of unknown significance (VUS) was present in all six tumor specimens." (PMID 41331048, 2025). "Moreover, clone formation, wound-healing, and transwell assays confirmed that TRIM24 overexpression couldn’t reduce the anti-tumor effect of K430R-NRBP1." (PMID 41430038, 2025). "IACS-9571, a selective high affinity small molecule inhibitor targeting at the bromodomain domain of TRIM24, has been found and is expected to be put into further clinical research, which provides the possibility for TRIM24 to become a clinical therapeutic target of tumor." (PMID 35105347, 2022). "Moreover, recent studies on various tumor models have shown that TRIM24 may promote tumorigenesis by affecting Akt pathway and cell cycle." (PMID 35105347, 2022). "Therefore, TRIM24 is independent of clinical risk factors and not influenced by the stage of the tumor." (PMID 35743773, 2022). "However, there has been a long-standing debate on whether TRIM24 functions as either a tumour suppressor or oncogene, and the answer appears to be context-dependent." (PMID 35595823, 2022). "Release of TRIM24-siRNA, followed by knockdown of TRIM24, significantly suppresses proliferation, colony-formation, and invasion of PSMA+ CRPC cells in vitro, and inhibits tumor growth of PSMA+ CRPC xenografts and bone loss in a PSMA+ CRPC bone metastasis model." (PMID 33287240, 2020). "Therefore, we speculated that Trim24 in macrophages is downregulated by the sensing of environmental factors during tumor pathogenesis." (PMID 31554795, 2019). "Interestingly, after collecting TAMs from WT and Trim24M−/− tumor-bearing mice through FACS sorting, much more Lys383-acetylated Stat6 was detected by immunofluorescent staining in the nuclei of WT TAMs than those of Trim24-deficient TAMs." (PMID 31554795, 2019). "In contrast to these reports, however, our study demonstrates for the first time that TRIM24 is reduced in ESCCs when compared with NCETs, as judged by qRT-PCR, Western blot and immunohistochemistry, which suggests that TRIM24 may be a tumor suppressor in ESCC." (PMID 27689360, 2016). "Aberrant expression of TRIM24 might promote tumor development by multiple mechanisms." (PMID 22666376, 2012). "TRIM24 knockdown significantly reduced tumor fluorescence values in MKN74- and NUGC3-orthotopic tumor models." (PMID 41430038, 2025). "Our findings show that the TRIM24::NTRK2 fusion initially had oncogenic abilities, but this became less imperative as the tumor evolved." (PMID 41331048, 2025). "In the B16 melanoma tumor model, STAT6 induces M2 macrophage polarization and inhibits TRIM24 expression in M2 macrophages, thereby inducing an immunosuppressive tumor niche." (PMID 40131539, 2025). "TRIM24 enhances cell proliferation and migration in human HCC in vitro and accelerates tumor progression in vivo, primarily through AMP-activated protein kinase (AMPK) signaling." (PMID 39160596, 2024). "Like TRIM24, TRIM28 is typically considered as an oncogene, which is expressed higher in tumor tissue when compared to adjacent healthy tissue in various cancers." (PMID 39160596, 2024).
tumor (continued). "Samples of the pre-treatment (TRIM24-MET-i) and recurrent tumor (after chemotherapy but before cabozantinib; TRIM24-MET-r) were obtained for further characterization and disease modelling." (PMID 38849845, 2024). "TRIM24 negatively regulates STAT1 in HNSCC, contributing to immunosuppression in cancer cells while enhancing T cell antitumor immunity in the tumor microenvironment, whereas, the precise mechanism remains elusive." (PMID 39160596, 2024). "Consistent with tumor suppression, effectors of tumorigenesis (Myc, Myb, NKX2-3, and TRIM24), metastasis (NFE2L2), oncogenic transformation (FOXM1), and cell cycle (E2F2 and E2F3) were also inhibited in the presence of PRKN." (PMID 39213189, 2024). "To further investigate the therapeutic vulnerability of the pharmacological inhibition of DNA‐PKcs on TRIM24‐induced Ep‐GBM‐like tumor progression, we first assessed the effects of NU7441 on NHA/HRasV12/TRIM24 cells." (PMID 38828688, 2024). "To investigate capmatinib's anti-tumor efficacy on human cells in vivo, we established a novel PDOX model using TRIM24-MET-i cells." (PMID 38849845, 2024). "Compared with animals bearing TRIM24 WT tumor xenografts, animals with NHA/HRasV12/TRIM24 S767/768A tumor xenografts showed prolonged survival." (PMID 38828688, 2024). "For example, TRIM24 overexpression is related to HCC onset and progression, and functions as a tumor promoter by downregulating AMPK levels." (PMID 37958377, 2023). "Other TRIMs, such as TRIM15, TRIM11 and TRIM24, have also been proved to be closely related to the EMT process, leading to tumor metastasis." (PMID 36249749, 2022). "Some members of TRIM family proteins play an important role in tumor occurrence and development, for example, TRIM8, TRIM24, TRIM28, and TRIM32 are found to be highly expressed in malignant tumor tissues and participate in the malignant biological behavior." (PMID 36249749, 2022). "The proportion of TRIM24+ tumors is significantly lower in pharyngeal HNSCC, than in laryngeal HNSCC (n = 100, p < 0.001) or in tumors of the oral cavity (n = 79, p = 0.001)." (PMID 35743773, 2022). "There is therefore a strong rationale to exploring TRIM24 as a target in HNSCC treatment, which can potentially leverage the STAT1 pathway to improve HNSCC tumour outcomes." (PMID 35595823, 2022). "TRIM24 also binds to the RARE of STAT1 promoter to inhibit STAT1 expression and promotes expressions of tumor-suppressive factors such as p21, Bmyc, and hepatocyte nuclear factor 6 (HNF6)." (PMID 36100865, 2022). "We leveraged our finding that TRIM24 directly activates Met expression and TRIM24COE tumor-derived primary cells to test the potential of therapeutically targeting MET." (PMID 34508101, 2021). "As to how HAT1 regulates AR expression, there are multiple transcriptional factors, such as MYC, EZH2, TRIM24, KLF4, and BRD4, regulate AR transcription by binding to its promoter in tumor cells." (PMID 34323404, 2021). "There are multiple transcriptional factors, such as MYC, EZH2, TRIM24, KLF4, and BRD4, that can regulate AR transcription by binding to its promoter in tumor cells." (PMID 34323404, 2021). "TRIM24 and TRIM56 were found to interact with ERα, stabilizing its chromatin interactions, thereby enhancing estradiol-stimulated tumor cell proliferation." (PMID 34208621, 2021). "In contrast, a few members including TRIM8, TRIM15, TRIM24, and TRIM40 are characteristically downregulated in CRC and exert tumor-suppressive activities." (PMID 33066016, 2020). "However, in the tumor microenvironment, activated Stat6 could directly mediate the transcriptional suppression of Trim24 in M2-polarized macrophages, in which low levels of Trim24 were insufficient to mediate CBP ubiquitination and Stat6 acetylation." (PMID 31554795, 2019). "Among these, TRIM24, TRIM26 were identified as tumor suppressors in the development of HCC, whereas TRIM31 was identified as a tumor promoter for HCC5,15,19." (PMID 29789583, 2018).
tumor (continued). "To verify the manipulation of these proteins at the endpoint, we performed IHC in tumor tissue sections and found that both TRIM28 and TRIM24 protein stained predominantly in the nuclei and their staining intensities were decreased in TRIM28-knockdown tumors." (PMID 30479348, 2018). "To examine the tumorigenic roles of TRIM28 in vivo, we inoculated control, TRIM28-knockdown, or TRIM28-knockdown and TRIM24-re-expressing C4-2B cells into SCID mice and monitored xenograft tumor growth." (PMID 30479348, 2018). "Patients with TRIM24 overexpression showed poor differentiation, higher level of AFP, higher incidence of intrahepatic metastasis and recurrence, and shorter Tumor-free survival time." (PMID 24409330, 2014). "In this study, we measured both mRNA and protein levels of TRIM24 and found that TRIM24 expression was increased in the HNSCC cell lines and primary tumor tissues at both mRNA and protein levels." (PMID 23717505, 2013). "Like TRIM24/TIF1α and TRIM32, TRIM16 has been shown to suppress tumour progression through regulatory pathways involved in growth inhibition, migration, differentiation and apoptosis." (PMID 23404198, 2013). "Subsequently, we performed COX regression analysis on variables such as sex, age, tumor location, differentiated degree, TNM stage, and TRIM24 expression, and found that M stage and high TRIM24 expression were both independent adverse prognostic factors for GC patients." (PMID 41430038, 2025). "Mechanistically, phosphorylation at the S42 residue may be a critical prerequisite for TRIM24 to recognize and degrade NRBP1, thereby modulating its tumor-suppressive function." (PMID 41430038, 2025). "Furthermore, TRIM24 downregulation remarkably reduced MKN74- and NUGC3-orthotopic tumor sizes and tumor weights." (PMID 41430038, 2025). "Notably, TRIM24 knockdown markedly inducted apoptosis in GC cells through the modulation of NRBP1, a known context-specific tumor suppressor." (PMID 41430038, 2025). "Since tumor‐intrinsic transcriptional subtypes correlate with tumor microenvironment (TME) heterogeneity, we further compared TME heterogeneity between HRasV12/TRIM24 and control tumors." (PMID 38828688, 2024). "Because OC is primarily a tumor of epithelial origin, the expression of TRIM proteins was analyzed in epithelial cells, and the eight most highly expressed genes (TRIM28, TRIM27, TRIM33, TRIM38, TRIM47, TRIM56, TRIM8, and TRIM24) were determined." (PMID 38881325, 2024). "The PSMAb-mediated TRIM24 siRNA delivery platform demonstrated significant inhibition of cell proliferation, colony formation, and invasion in PSMA-positive CRPC in vitro, and suppression of tumor growth in a xenograft model." (PMID 39160596, 2024). "Our study showed that overexpression of TRIM24 increased the level of p-Akt in EOC cells, while interfering TRIM24 reduced the level of p-Akt, suggesting that TRIM24 may promote the tumor progression of EOC by promoting phosphorylation of Akt." (PMID 35105347, 2022). "The positive correlation between TRIM24 and DDX27 was also found in collected CRC tumor samples." (PMID 36551703, 2022). "Despite TRIM24 being described to be found mainly in the nuclei of tumor cells, we could show a broad variety of expression patterns of TRIM24 in HNSCC tumor cells." (PMID 35743773, 2022). "Our results confirmed that TRIM24 could predict poor prognosis of EOC patients and promote tumor progression by regulating Akt pathway and EMT." (PMID 35105347, 2022). "The TRIM24-PLXNA4 fusion was also detected by Arriba, suggesting that it is expressed in the tumor." (PMID 36503484, 2022). "Given that TRIM24 was selectively expressed in tumour cells of the HNSCC microenvironment potentially provides an opportunity for selectively targeting STAT1 and mitigating its tumour promoting effects in HNSCC in vivo." (PMID 35595823, 2022). "We further identified that Linc00963 could promote tumor growth of CRPC cells by inhibiting miR-655 and upregulating TRIM24 axis in vivo." (PMID 33643926, 2021).
tumor (continued). "Finally, we elucidated that Linc00963 promoted cell proliferation and tumor growth of CRPC cells in vitro and in vivo by sequestering miR-655 and then upregulating TRIM24 expression." (PMID 33643926, 2021). "In addition, the SPOP protein plays a role as a tumor suppressor that negatively regulates the stability of multiple other oncogenic substrates in PrCa, including AR, SRC-3, c-MYC, ERG, DEK, BRD4 and Trim24." (PMID 34857003, 2021). "Analyses of several cell lines and tumor samples showed a negative correlation between TRIM24 and miR-137 expression." (PMID 34208621, 2021). "Whereas, the relative expression of TRIM24 and miR-655 were not changed significantly in the resected tumor tissues of Lv-Linc00963-MUT group and Lv-control group (P>0.05)." (PMID 33643926, 2021). "Re-expression of TRIM24 showed a trend in rescuing tumor growth but the change was not statistically significant." (PMID 30479348, 2018). "When various engineered U87 cells were implanted into the brains of animals, knockdown of endogenous TRIM24 by two separate shRNAs significantly reduced EGFRvIII-stimulated tumor growth relative to non-silencing control xenografts." (PMID 29129908, 2017). "Furthermore, miR-511 elicits tumor-suppressive effects through inactivating PI3K/AKT and Wnt/β-catenin pathways by suppressing TRIM24." (PMID 28114950, 2017). "TRIM24 protein is reduced in ESCC, which implies that it functions as a tumor suppressor in ESCC." (PMID 27689360, 2016). "A strong staining of TRIM24 was detected in adjacent tumor cells, while negative or low staining of TRIM24 was detected in the normal liver tissues." (PMID 24409330, 2014). "Elevated TRIM24 level was found in 61.4% HCC samples (51/83) correlating with AFP (P = 0.036), poor differentiation (P = 0.004), intrahepatic metastasis (P = 0.004), recurrence (P = 0.000006), and shorter tumor-free survival time (P = 0.002)." (PMID 24409330, 2014). "We investigated TRIM24 protein expression pattern using immunohistochemical staining in 91 tumor samples from patients with locally advanced HNSCC and analyzed the correlations between TRIM24 expression and clinical outcome using Kaplan-Meier survival analysis." (PMID 23717505, 2013). "No statistical difference was found between the TRIM24 overexpression and the characteristics of age (p = 0.4697), gender (p = 0.1814), tumor status (p = 0.1812), nodal status (p = 0.0825) and tumor type (p = 0.6327)." (PMID 22666376, 2012). "However, our results point to TRIM24::NTRK2 not being the only driver in this tumor, but is likely a combination with CDKN2A/B HD, pTERT, and other acquired alterations in later relapses." (PMID 41331048, 2025). "Importantly, findings from the liver metastasis model indicated that the enhanced metastatic potential conferred by TRIM24 was not entirely dependent on primary tumor size." (PMID 41430038, 2025). "The results showed that TRIM24 overexpression significantly enhanced the liver metastatic capacity of GC cells, and this enhanced metastatic ability was not entirely dependent on the size of the primary tumor." (PMID 41430038, 2025). "Kaplan–Meier survival analysis showed that TRIM24 expression increased inversely with the clinical prognosis of patients with EOC, which was consistent with previous study in that the higher level of TRIM24 is correlates with tumor metastasis and worse survival in EOC patients." (PMID 35105347, 2022). "Additionally, while TRIM24 expression is low in tumour-infiltrating lymphocytes, its downregulation could, in turn, upregulate STAT1 anti-tumour activity." (PMID 35595823, 2022).
tumor (continued). "SPOP has been shown to participate in diverse cellular processes and plays tumor suppressive and oncogenic roles in PrCa by targeting different substrates for ubiqutination-mediated proteolysis, including AR, steroid receptor coactivator 3 (SRC-3), DEK, TRIM24, BRD4 and Nanog." (PMID 34857003, 2021). "Consistently, the Trim24M−/− mice displayed notably increased tumor infiltration of CD11b+F4/80+ macrophages, whereas the infiltration of myeloid-derived suppressor cells (MDSCs) and dendritic cells was not affected by Trim24 ablation." (PMID 31554795, 2019). "Re-expression of TRIM24-WT* rescued EGFRvIII-driven tumor growth, whereas re-expression of TRIM24-F979A/N980A* could not." (PMID 29129908, 2017). "Taking our results together with those of previous studies, we supposed that TRIM24 may function as a tumor suppressor in ESCC independent of RARα-dependent transcription." (PMID 27689360, 2016). "More interestingly, patients with TRIM24 overexpression showed poor differentiation (P = 0.004), higher level of AFP (P = 0.036), higher incidence of intrahepatic metastasis (P = 0.004) and recurrence (P = 0.000006), and shorter Tumor-free survival time (P = 0.002)." (PMID 24409330, 2014). "Interestingly, in our orthotopic HNSCC model, we found that TRIM24 expression is high in HNSCC cells but not in tumour-infiltrating T lymphocytes, suggesting the potential of targeting TRIM24 to modulate STAT1 signalling specifically in HNSCC cells but not T cells." (PMID 35595823, 2022). "The exposure of TRIM24-depleted tumors, but not their wild type counterparts, to BTZ, led to a 43% decrease in tumor weight, while this effect was not improved by the addition of dTRIM24." (PMID 40097385, 2025). "Pathway analysis of RNA sequencing data from tumours from Stat1+/+ and Stat1−/− mice orthotopically injected with LY2 HNSCC cells also identified TRIM24 as the top predicted negative transcriptional regulator of STAT1 during HNSCC in our data set (z score –5.804, p value 1.32 × 10−16)." (PMID 35595823, 2022). "Cytoplasmic TRIM24 reportedly ubiquitinates TRAF3 and facilitates antiviral immunity, a function that may not be relevant to MpBC tumor development and patient survival." (PMID 34508101, 2021). "Furthermore, other female-biased genes that have been identified as tumor suppressors in the context of HCC, such as Trim24, were not up-regulated in male E1/E2-KO liver." (PMID 32428001, 2020).